BDNF (brain derived neurotrophic factor)
Diseases named in the same sentence as BDNF in open-access papers (continued):
Sharing a sentence is not in itself a finding about the gene and the disease.
Obesity (continued). "This study suggests that the anxiolytic effect and activation of the BDNF signaling by ASH extract improve the exacerbation in obesity-related pathological changes." (PMID 30602695, 2018). "Indeed, whereas the correlation between obesity and hypothalamic BDNF reduction in both human and animal models is well established, the association of this pathology with circulating BDNF derives predominantly only from the assumption that circulating BDNF mirrors the one in the brain." (PMID 30081509, 2018). "Taken together, BDNF functions to counteract obesity through reducing energy intake and enhancing energy expenditure." (PMID 30555354, 2018). "Inclusion of these measures would provide a more comprehensive understanding of the complex relationships between BDNF, metabolic outcomes, and cognition in response to exercise training in adolescents with obesity." (PMID 30363954, 2018). "Due to the high rates of both obesity and dyslipidaemia in PTSD, the aim of this study was to elucidate the association of BDNF Val66Met and BDNF C270T polymorphisms with BMI and lipid levels in veterans with PTSD." (PMID 30542302, 2018). "Due to high rates of obesity and dyslipidaemia in PTSD, the aim of this study was to elucidate the association of BDNF Val66Met and C270T polymorphisms with BMI and lipid levels in veterans with PTSD." (PMID 30542302, 2018). "The present study attempts to provide an analysis of epidemiological and genetic data towards the possible mechanism of the role of MC4R or BDNF in obesity." (PMID 28396685, 2017). "Fetal or early postnatal depletion of BDNF or its receptor, TrkB, in rodents results in hyperphagia and severe obesity." (PMID 29062839, 2017). "Systemic and intracerebroventricular administration of BDNF lowered blood glucose, decreased body weight, reduced hepatomegaly, and liver glycogen content in experimental animals with obesity and diabetes." (PMID 28824543, 2017). "Previously, BDNF was shown to modulate obesity, diabetes, hypertension, and dyslipidemia, each of which is a traditional risk factor for CKD." (PMID 28575038, 2017). "These novel findings provide important evidence that adiponectin possibly mediates MC4R and BDNF involved in obesity." (PMID 28396685, 2017). "We observed a lower expression of hippocampal BDNF in rats assigned to the HH group compared to rats assigned to the CC, HC, and HH groups, suggesting, an additive effect of maternal high-fat diet/obesity and a postnatal high-fat diet." (PMID 29340106, 2017). "BDNF is also involved in the pathogenesis of obesity, type 2 diabetes mellitus, and metabolic syndrome." (PMID 29340106, 2017). "BDNF also regulates food consumption, as conditional KO mice in which BDNF has been centrally deleted show obesity and hyperactivity." (PMID 29375393, 2017). "The BDNF AUC index was significantly greater in the obesity group than in the control group (9.0 ± 16.5 vs. −8.0 ± 22.5, P = 0.001)." (PMID 27787389, 2016). "Rodent studies in which obesity has been induced during pregnancy using high fat diets, have demonstrated increased inflammatory cytokines, lower levels of brain-derived neurotrophic factor (BDNF) in the offspring brain and poorer learning." (PMID 27520466, 2016). "In rodents, pharmacological treatments with BDNF induce a reduction of food intake, whereas genetic models with reduced BDNF/TrkB signaling display hyperphagia and obesity." (PMID 26740873, 2016). "Using multivariate regression analysis, obesity was identified as an independent factor for a high BDNF AUC index after adjustment for age, CRP, and PC 2 hours glucose." (PMID 27787389, 2016). "Diet-induced obesity reduces hippocampal expression of BDNF and presynaptic synaptophysin, which are related to an impairment of spatial learning in mice." (PMID 26881095, 2016). "In contrast, animal studies have shown that BDNF heterozygous (HT) mice exhibit hyperphagia, obesity, and increased locomotor activity, while knockout (KO) of BDNF is lethal." (PMID 27861553, 2016).
Obesity (continued). "In the present study, we reported a greater increment of serum BDNF concentration as demonstrated by the BDNF AUC index after glucose intake in men with obesity and metabolic syndrome than in controls." (PMID 27787389, 2016). "To better understand the alterations in serum BDNF after glucose loading in subjects with obesity, we assessed the serum BDNF concentrations during a 2-hour glucose tolerance test (OGTT) between subjects with obesity and controls." (PMID 27787389, 2016). "Chronic HFD consumption results in central and peripheral leptin resistance, thereby preventing the neuroprotective role of leptin in obesity and potentially contributing to the downregulation of BDNF after chronic HFD consumption." (PMID 26260473, 2015). "The results indicate BDNF and leptin play major roles in central regulation of energy metabolism and dysregulation of the neurotrophin signaling result in obesity." (PMID 26089796, 2015). "While BDNF levels in the CNS declines with age, diet-induced obesity lowers hippocampal synaptic plasticity, BDNF levels and cognition by itself, at least in rodents." (PMID 26041981, 2015). "The circulating BDNF concentrations are also decreased in subjects with obesity or metabolic syndromes." (PMID 25918454, 2015). "Clinically, disruption of POMC, PCSK1, BDNF, and NTRK2 is associated with severe early-onset obesity." (PMID 25806089, 2015). "The adipose tissue BDNF/TrkB axis has a substantial influence on the feeding behavior and obesity in female mice." (PMID 28721258, 2015). "Even heterozygous mice with 50% reduced levels of BDNF expression display some behavioural deficits such as aggressiveness, hyperactivity, hyperphagia and obesity." (PMID 26223433, 2015). "In a previous study, BDNF heterozygous knockout (BDNF +/−) mice showed obesity and insulin resistance." (PMID 25587547, 2014). "rs10767664 (BDNF) and rs3751812 (FTO) provided the strongest evidence of an association with obesity with odds ratios of 1.923 (CI: 1.32–2.81, P = 0.00072) and 1.523 (CI: 1.08–2.15, P = 0.016), respectively." (PMID 25484485, 2014). "At least two CNVs, of SIM1 at 6q16 and BDNF at 11p14, are well known to include obesity as a phenotype." (PMID 25411582, 2014). "In the presented study, we tried to establish the role of SF-1 in the regulation of human BDNF, an important player for central energy balance and thus obesity." (PMID 25122490, 2014). "Although the relationship between obesity and regulators of synaptic function including BDNF remain to be elucidated, current research is underway." (PMID 25309465, 2014). "The hyperphagic childhood obesity associated with loss of BDNF expression or loss of TrkB is highly reminiscent of that seen in BBS and other obesity ciliopathies." (PMID 24867303, 2014). "Loss of BDNF-mediated activation of TrkB results in phenotypes reminiscent of BBS, included hyperphagia-driven obesity." (PMID 24867303, 2014). "Additional evidence of a role for BDNF in obesity comes from a knock-in mouse strain, which contains the Val66Met mutation and exhibits increased body weight." (PMID 23519010, 2013). "Animals with heterozygous knockout of BDNF, haploinsufficiency, or postnatal BDNF deletion in the central nervous system exhibit progressive obesity." (PMID 25089225, 2013). "Mice heterozygous for BDNF develop obesity related to hyperphagia while BDNF administration in rats promotes weight reduction by causing loss of appetite." (PMID 23670594, 2013). "SNPs in the FTO, GNPDA2, SEC16B, BDNF, TMEM18 and NPC1 loci associated with increased risk of both overweight and obesity." (PMID 23861046, 2013). "After adjusting for age, sex and admixture, significant associations with obesity were found for 6 genes in the case-control study (ADIPOQ, FTO, TMEM18, INSIG2, FAIM2/BCDIN3 and BDNF)." (PMID 23950976, 2013).
Obesity (continued). "In several animal models of obesity and diabetes, including db/db mice, diet-induced obesity mice and lethal yellow agouti mice, peripheral administration of BDNF has been shown to prevent or ameliorate the diabetic and obese phenotypes." (PMID 23519010, 2013). "Intracerebroventricular (icv) BDNF injection markedly reduced body weight in several obesity models by reducing appetite and increasing energy expenditure." (PMID 24106476, 2013). "Other loci, including the INSIG2, TMEM18, KCTD15, SH2B1, MTCH2, GNPDA2, BDNF, or CHST8 genes, have also been associated with obesity." (PMID 24267414, 2013). "Obesity risk was nominally associated with variation at the FAIM2 locus (OR = 1.58, 95% CI: 1.05–2.40, p = 0.025), and with a variant at the BDNF locus (OR = 1.72, 95% CI: 1.00–2.95, p = 0.028)." (PMID 23347264, 2013). "One study showed a significant positive relationship between BDNF and obesity, and another found that BDNF negatively correlated with both BMI and body fat." (PMID 25089225, 2013). "Collectively, these studies show that BDNF levels in some brain regions change in response to nutritional status and that postnatal ablation of BDNF expression leads to hyperphagia and obesity." (PMID 23519010, 2013). "Mice with BDNF haploinsufficiency exhibited obesity and elevated levels of GLU, whereas systemic peripheral administration of BDNF contributed to the improvement of GLU metabolism and prevented the development of diabetes." (PMID 23967328, 2013). "Given the crucial role of BDNF in neuronal development, it is conceivable that developmental defects in neural circuits also contribute to the massive obesity observed in mice with impaired BDNF activity." (PMID 23519010, 2013). "Based on evidence of heterogeneity, we examined the relationship of BDNF and obesity traits by gender." (PMID 25089225, 2013). "Animals with reduced BDNF expression due to a conditional knockout in the brain develop hyperphagia, obesity and resistance to insulin." (PMID 23431394, 2013). "Earlier studies have demonstrated that BDNF is involved in regulation of food intake, obesity and energy homeostasis." (PMID 23861046, 2013). "Diminished BDNF signaling results in hyperphagia and obesity, whereas an increase in BDNF signaling has the opposite effect." (PMID 22548651, 2012). "Other signals near BDNF, SH2B1, and NEGR1 (all implicated in aspects of neuronal function) reinforce the view of obesity as a disorder of hypothalamic function." (PMID 22474595, 2012). "Haplo-insufficiency for BDNF, TrkB and SIM1 has been associated with severe hyperphagic obesity, accompanied by syndromic features in humans." (PMID 22043164, 2011). "The two susceptibility loci for obesity reported here, KCNMA1 and BDNF displayed nominal allelic association with obesity in each investigated adult case-control cohort." (PMID 21708048, 2011). "Three reported susceptibility loci for obesity harbour genes that are known to be involved in catabolic hypothalamic pathways (MC4R, PCSK1, and BDNF) and many others contain genes that are highly expressed in the central nervous system." (PMID 21708048, 2011). "It has been shown recently that plasma BDNF levels are reduced in patients with type 2 diabetes (independently of obesity), and are inversely correlated with fasting plasma glucose." (PMID 20404913, 2010). "By further analysing these adult obesity susceptibility loci in the ALSPAC birth cohort, with the addition of variants in BDNF and ETV5, we aimed to identify the specific timing of childhood weight gain and growth associated with adult obesity risk." (PMID 20520848, 2010). "The obesity-risk-allele score based on genotypes at eight SNPs associated with childhood BMI (in/near to: FTO, MC4R, TMEM18, GNPDA2, NEGR, KCTD15, BDNF, and ETV5) ranged from 2 to 15 alleles." (PMID 20520848, 2010). "For example, the mice used by Chan and colleagues exhibit hyperactivity, obesity and aggressiveness, similar to the phenotypes seen in BDNF+/- mice." (PMID 20025751, 2009).
Obesity (continued). "Additionally, physical exercise has been shown to elevate BDNF levels, suggesting a therapeutic opportunity for obesity management." (PMID 41082226, 2025). "Therefore, aging, obesity, and exercise appear to affect white adipose tissue to regulate the hippocampus BDNF level." (PMID 40724847, 2025). "Obesity is also recognized as an inflammatory inducing state, and it has been reported that BDNF may be elevated in some older adults with obesity/metabolic syndrome as a compensatory mechanism to protect the brain from an inflammatory insult." (PMID 39421964, 2025). "Notably, certain genes such as MC4R, BDNF, and PCSK1 are implicated in both monogenic and polygenic obesity, depending on the type and frequency of the variant." (PMID 40281302, 2025). "Dysregulation of adipose CX3CL1 may contribute to decreased BDNF levels in the hippocampus with obesity." (PMID 40724847, 2025). "Reciprocally, obesity accelerates cognitive aging via the dysregulation of BDNF." (PMID 40724847, 2025). "Reduced BDNF levels could contribute to beta cell dysfunction, reduced muscle oxidative capacity, and altered eating behavior promoting obesity and T2D." (PMID 40171198, 2025). "Furthermore, both obesity and psychological stress are associated with reduced bioavailability of BDNF, brain-derived neurotrophic factor (BDNF)." (PMID 40104146, 2025). "Additionally, the relatively short duration of the intervention precluded an examination of the long-term effects of energy-restricted diets on obesity and changes in blood BDNF levels." (PMID 40697550, 2025). "Similarly, obesity-driven metabolic dysregulation disrupts the secretion of neuroprotective factors such as brain-derived neurotrophic factor (BDNF) and insulin-like growth factor 1 (IGF-1), reducing neuronal viability and limiting neurorepair capacity." (PMID 40332538, 2025). "Therefore, obesity appears to decrease the BDNF level in the brain, which is consistent with the finding that obesity accelerates brain aging, as discussed in the previous section." (PMID 40724847, 2025). "Obesity, T2DM, and PD are all linked to altered BDNF levels as indicated in our study." (PMID 40088335, 2025). "Compared with wild-type mice, BDNF heterozygous mice exhibited obesity and hyperactivity." (PMID 40283892, 2025). "Mutations in the Dlk1 gene result in precocious puberty and obesity; however, it is currently unknown if this phenotype is due to abnormalities in the functions of VMH DLK1 neurons, and if BDNF is somehow involved in the pathophysiology of the diseases." (PMID 41219904, 2025). "It would be tempting to speculate that in obesity NGF overexpression causes hyperinnervation, however, evidence suggests that in obesity‐related metabolic disorders NGF and brain derived neurotrophic factor signaling is reduced." (PMID 39825711, 2025). "Decreased levels of BDNF expression have been observed in individuals with obesity and may impair the maintenance and function of dopaminergic neurons." (PMID 40655479, 2025). "The aim of this study was to investigate the effects ofquercetin on obesity and ovarian tissue by analyzing the expression of genesinvolved in the hypothalamus-pituitary-gonadal axis, includingob-Rb, ob-Ra, and brain-derived neurotrophic factor(Bdnf), neuropeptide Y (NPY), andKisspeptin (Kiss-1)." (PMID 39983030, 2025). "The BDNF gene was recently shown to be involved in obesity-related pathways in obese children." (PMID 40598589, 2025). "While aging and obesity decrease the BDNF level, exercise and fasting increase it." (PMID 40724847, 2025). "Metabolic function is a critical determinant of diet sensitive BDNF signaling with a potential role for insulin resistance, obesity, and chronic inflammation blocking BDNF-related pathways and critical PI3K/Akt and AMPK signaling to engage synaptic plasticity and neuronal cell survival." (PMID 40362507, 2025). "SH2B1 counteracts energy imbalance and obesity at least in part by enhancing BDNF action." (PMID 38885417, 2024).
Obesity (continued). "Exercise may offer a non‐pharmacological approach to counteract obesity‐related reductions in BDNF levels, potentially mitigating cognitive decline and neurodegenerative disease development." (PMID 38988101, 2024). "According to this, it was notified that circulating BDNF level significantly increased, decreased, and remained unchanged after exercise intervention in patients with obesity." (PMID 38785805, 2024). "Based on these studies, the rise of circulating BDNF levels, which are lower baseline in patients with obesity compared to normal-weight individuals, following high-intensity exercise may be related to decreased hunger and an increased sense of fullness." (PMID 38785805, 2024). "Furthermore, while emerging evidence suggests that physical exercise can modulate circulating BDNF levels, its impact on individuals with obesity remains to be fully elucidated." (PMID 38785805, 2024). "Additionally, given the complex processes regulating BDNF levels in tissues, it is challenging to explain the relationship between BDNF and obesity." (PMID 38785805, 2024). "Moreover, BDNF knockout leads to obesity, indicating that adipocytic BDNF is essential for the central-peripheral BDNF regulatory loop, which integrates central appetite signals and adipokine levels." (PMID 39655343, 2024). "In this context, it is important to conduct quality and randomized controlled studies with larger sample groups, considering the energy intake of the participants in order to elevate circulating BDNF in response to exercise intervention in patients with obesity." (PMID 38785805, 2024). "In contrast, central BDNF knockdown leads to obesity and elevated leptin expression in adipocyte." (PMID 39655343, 2024). "Thus, more studies are needed to provide a clearer understanding of which type of physical activity has the greatest impact on circulating BDNF in patients with obesity." (PMID 38785805, 2024). "This suggests that the possible impact of increased BDNF levels following acute high-intensity exercise on substrate utilization may enhance the management of metabolic disorders related to obesity." (PMID 38785805, 2024). "These components are critical determinants of the physiological responses to exercise, and their nuanced exploration could provide valuable insights into the specific parameters influencing circulating BDNF levels in individuals with obesity." (PMID 38785805, 2024). "Additionally, central BDNF knockdown leads to hyperphagia and obesity, while the knockout of Trek B in adipocytes reduces HDF-induced obesity in female conditional knockout mice, but this effect is not observed in males." (PMID 39655343, 2024). "Our hypothesis suggests that physical exercise has the potential to elevate circulating BDNF levels in individuals with obesity, thus potentially alleviating neurobiological impairments associated with the condition and enhancing brain health." (PMID 38785805, 2024). "Adipocyte-specific deletion of BDNF/TrkB results in resistance to HFD-induced obesity, particularly in females,indicating that adipocytic BDNF is essential for the adipocytic response to central BDNF signaling and the production of adipocytokines, including leptin." (PMID 39655343, 2024). "Therefore, this study aimed to explore the impact of acute and regular physical exercise on circulating BDNF in individuals with obesity." (PMID 38785805, 2024). "Well designed and quality randomized controlled studies with greater populations are recommended to determine how different exercise configurations may affect circulating BDNF levels in patients with obesity." (PMID 38785805, 2024). "For individuals with a low genetic risk of obesity by FTO, MC4R and BDNF, the effect of water intake on abdominal adiposity may be more pronounced." (PMID 38662725, 2024).